IGHV3OR16-9 (immunoglobulin heavy variable 3/OR16-9 (non-functional))
Synonyms: IGHV3/OR16-9; IGHV3OR169
Gene: Immunoglobulin variable (V) gene on chromosome 16 (32,066,065 to 32,066,358, forward strand). Ensembl gene ENSG00000270472.
Gene Ontology:
Molecular function: antigen binding
Biological process: immunoglobulin mediated immune response
Cellular component: extracellular region; plasma membrane
Homologues: Paralogues in human: IGHV3OR16-8 (93% identical), IGHV3OR16-17 (91% identical), IGHV3-11 (88% identical), IGHV3-23 (87% identical), IGHV3-21 (85% identical), IGHV3-48 (85% identical), IGHV3-64D (84% identical), IGHV3-66 (83% identical), IGHV3-35 (82% identical), IGHV3-53 (82% identical), IGHV3-7 (82% identical), IGHV3-72 (82% identical), and 65 more.